SOX9 (SRY-box transcription factor 9)
Diseases named in the same sentence as SOX9 in open-access papers (continued):
Sharing a sentence is not in itself a finding about the gene and the disease.
tumor (continued). "Upregulation of Sox9 (by qPCR) in HCC was associated with poorer tumor cell differentiation (p = 0.003), venous invasion (p = 0.026), higher tumor stage (p = 0.044) and shorter overall survival." (PMID 27105493, 2016). "A study of SOX9 protein expression in both surgically resected tumor tissue and serum specimens of hereditary multiple myeloma (HME) confirmed the increased SOX9 expression levels in the HME sera and tissues, compared with those of the control group." (PMID 28090537, 2016). "By gain and loss-of-function studies in SW480 and SW620 cells respectively, we reveal that SOX9 levels modulate tumorsphere formation and self-renewal ability in vitro and tumor initiation in vivo." (PMID 27571710, 2016). "Overall, 94% of SQCCs expressed SOX2, with most tumor cells expressing moderate to high levels, and 73% had detectable levels of SOX9, although in the majority of cases SOX9 was expressed in very few tumor cells and at low levels." (PMID 27880766, 2016). "Instead, secondary events, such as inflammation-induced signaling activation of the epidermal growth factor (EGFR) or induction of Sox9 expression, are required for tumor formation." (PMID 26697077, 2016). "SOX9 has decreased expression in cervical carcinoma compared to normal cervical tissue, and in vitro inhibited cell growth and tumor formation when overexpressed." (PMID 27248473, 2016). "While in HCC, suppression of Sox9 by miRNA-101 and miRNA-145 inhibits tumor proliferation, migration and invasion." (PMID 27105493, 2016). "This was confirmed in vivo with subcutaneous grafts of S9-DLD-1 cells in nude mice since the tumor size was significantly reduced in response to doxycycline induced SOX9 expression." (PMID 27429045, 2016). "ELISA assays showed expression of the marker for pancreatic ductal lineage, SOX9, in the exocrine pancreatic cells and tumor cells harvested by laser capture micro-dissection." (PMID 27281617, 2016). "In the context of cancer, SOX9 has been classified as both tumor suppressor and oncogene depending on the study and type of cancer being investigated." (PMID 27248473, 2016). "MACC1 and SOX9 show a progressive increase in tumour and metastases compared to normal tissue with a median log 2 expression value increase from 6.8 to 8.7 in normal cells, and from 8.0 to 8.8 in primary tumour cells." (PMID 27463018, 2016). "Comparison of adjacent benign and tumor tissue revealed a significant increase in SOX9 mRNA expression in TMPRSS2:ERG fusion-positive tumors (P = 0.0012), while the expression of SOX9 in fusion-negative tumors resembled that of benign tissue (P = 0.60)." (PMID 27798103, 2016). "Here, the authors demonstrated that PML is also a potential therapeutic target in breast cancer where it specifically regulates cancer initiating cells and tumour progression through the transcriptional regulation of SOX9." (PMID 27553708, 2016). "This bi-potent differentiation ability of SOX9+ tumor was confirmed by FACS analyses of the tissue obtained from the serial transplantation experiments." (PMID 27457505, 2016). "Forced expression of β-catenin partially rescued the effect of Sox9 silencing on tumorsphere formation assays, and similarly the effects on tumorigenicity, tumor volume and tumor latency period in vivo." (PMID 27105493, 2016). "Consistent with the finding that SOX9 expression in the tumor was a good indicator of tumor recurrence, the serum OPN, but not AFP or PIVKA-II, level showed a significant correlation with the RFS in our analyses." (PMID 27457505, 2016). "Gli-1 additionally stimulates SOX9 transcription, which provides an explanation for the observed significant increase of SOX9 in tumor cells." (PMID 27281617, 2016). "The decreased expression of SOX9 dramatically inhibits the tumor growth and peritoneal metastasis in nude mice." (PMID 26755651, 2016).
tumor (continued). "The overexpression of SOX9 was observed in tumor tissues with higher tumor stage, poorer disease-free survival, and poorer overall survival of HCC patients." (PMID 27610139, 2016). "Initially, we performed subcutaneous grafts of S9-DLD-1 cells in nude mice and we observed a significant decrease of tumor growth upon induction of SOX9 expression with doxycycline-supplemented drinking water." (PMID 27429045, 2016). "Zygosity analysis was performed on 7 SOX9 expressing (IHC) CRC with SOX9 frameshift or nonsense mutations and high SOX9 mutant allele frequencies in comparison to estimated tumor percent." (PMID 27248473, 2016). "We also discovered that although SOX9 was generally expressed at low levels and in few tumor cells, its expression varied among SQCCs." (PMID 27880766, 2016). "The lower tumor-forming ability of SOX9− cells was confirmed in the serial transplantation of 1.0 × 104 cells (87.5% in SOX9+ cells and 12.5% in SOX9− cells)." (PMID 27457505, 2016). "In agreement, the silencing of SOX9 in HeLa cells promoted cell growth in culture and tumor formation in mice." (PMID 26036262, 2015). "It has been shown that SOX9 is overexpressed in cancers of the skin, prostate, lung, breast and brain, and contributes to tumor growth and invasion." (PMID 26036262, 2015). "The expression of p21 protein was consistent with the expression of SOX9 according to an immunohistochemical analysis of the tumor xenografts." (PMID 26036262, 2015). "Further, decreased expression of SOX9 dramatically inhibited the tumor growth and peritoneal metastasis in nude mice." (PMID 26009899, 2015). "In conclusion, our results suggest that SOX9 promotes tumor metastasis and invasion through regulation of S100P expression." (PMID 26009899, 2015). "In all of these cell types, the up-regulation of SOX9 protein inhibited cell proliferation and tumor formation, while the down-regulation of SOX9 promoted cell proliferation and tumor formation." (PMID 26036262, 2015). "Multiple studies involving 98–387 cancers had previously suggested a link between SOX9 expression and poor tumor features, such as high Gleason grade and even shortened overall patient survival." (PMID 26030748, 2015). "Cox multivariate analysis was carried out to identify if age, gender, TNM stage, and tumor type were significant contributing factors for 10-year survival of SOX9 high and SOX9 low patients." (PMID 25885555, 2015). "Further investigation would be required to determine if SOX9 would have early prognostic value for tumor malignancy." (PMID 25885555, 2015). "Additional support that SOX9 may be an important early event in the development of Barrett's tumorigenesis is seen in the activation of SOX9 following loss of β2-spectrin, which induces a TGFβ signaling switch from tumor suppressor in normal cells to tumor promoter in fibroblasts and EACs." (PMID 26447543, 2015). "SOX9, a transcription factor essential for both sex and skeletal development, has been reported as an oncogenic gene or tumor suppressor, and it plays essential roles in various tumors." (PMID 26384302, 2015). "Although the same number of cells was implanted (1×105 cells), the tumor formation rate of the SOX9-overexpressing cells (SiHa-SOX9 cells) was much lower than that of the control cells (SiHa-GFP cells) (p < 0.01)." (PMID 26036262, 2015). "We interrogated clinically relevant factors such as TNM staging, age, gender, and tumor type between the SOX9 high and SOX9 low group in the primary and metastatic datasets." (PMID 25885555, 2015). "The cytoplasmic presence of SOX9 in NIH3T3 fibroblasts and in invasive tumor cells shows involvement of SOX9 in epithelial mesenchymal transition, i.e. cells with a migratory, proliferative cellular phenotype." (PMID 26678612, 2015).
tumor (continued). "Similar to SOX4, SOX2 and SOX9 have also been shown to have tumor suppressive effects in specific cancer types (gastric cancer and melanoma, respectively), further emphasizing the context specific nature of SOX involvement in carcinogenesis." (PMID 25594027, 2014). "A recent study demonstrated that the upregulation of Sox9 in the acinar population is an early tumor-initiating event." (PMID 25405615, 2014). "Out of 10 available datasets comprising a total of 1,021 samples, 8 datasets with 762 samples showed statistically significant upregulation of Sox9 in lung ADC tumor tissue in comparison to normal adjacent tissue." (PMID 25004243, 2014). "The expression of SOX9 is up-regulated in a variety of human cancers, which correlates with tumor malignancy and progression." (PMID 24423398, 2013). "After chemotherapy there were 88% (72 of 82 cases) tumors with Sox9 expression in the tumor cells and 21% (19 of 84 cases cases) with expression in the tumor stroma." (PMID 24404438, 2013). "Sox9 is part of the prostate developmental pathway that is reactivated in prostate neoplasia where it promotes tumor cell proliferation and correlates with Ki67 expression." (PMID 23786676, 2013). "It has been seen that patients with elevated Sox9 levels in cytoplasm suffer from faster tumor cell proliferation and significantly shorter overall survival." (PMID 24404438, 2013). "The overexpression of SOX9 was observed in tumor tissues with higher tumor stage and higher tumor grade." (PMID 22515642, 2012). "Moderate to strong cytoplasmic staining of SOX9 was displayed in tumor cells from 135/142 (95.1%) paraffin-embedded archived NSCLC biopsy samples in comparison with the adjacent non-cancerous cells, which expressed little, if any, SOX9." (PMID 22385677, 2012). "All tumor cell lines showed significantly higher levels of SOX9 protein and SOX9 mRNA expression compared with NLEC, which showed no or marginal SOX9 expression." (PMID 22385677, 2012). "As part of a developmental pathway, elevation of SOX9 in prostate neoplasia promotes tumor cell proliferation." (PMID 22385677, 2012). "Our data suggest for the first time that the overexpression of SOX9 protein in HCC tissues is of predictive value on tumor progression and poor prognosis." (PMID 22515642, 2012). "As the results, we found that more SOX9 positive cells in the higher tumor stage (T3 ~ 4) and tumor grade (G3) than in the lower tumor stage (T1 ~ 2, P = 0.03) and tumor grade (G1 ~ 2, P = 0.01), respectively." (PMID 22515642, 2012). "MCL with methylated SOX9 (p = 0.001) or HOXA9 (P = 0.002) showed significant higher proliferation (Ki-67 index) than unmethylated tumours." (PMID 21603610, 2011). "In a series of 24 MCL with available CGH data, tumours with methylated SOX9 (P = 0.023) or HOXA9 (P = 0.006) showed a higher number of chromosomal abnormalities than unmethylated cases." (PMID 21603610, 2011). "It has been recently shown that NF1 tumours require for their growth the master regulator of cartilage differentiation SOX9." (PMID 21726432, 2011). "To explore the relationship between promoter methylation and gene expression in primary tumours we performed a qRT-PCR analysis of SOX9, HOXA9, AHR, ROBO1, and NR2F2 in a series of 36 MCL." (PMID 21603610, 2011). "It thus appears likely that MIA expression in NF1 tumours is also regulated by SOX9, as this transcription factor was reported to be required for the survival of MPNST cells." (PMID 21726432, 2011). "CpG arrays and MS-PCR in the discovery and validation sets of 10 pairs of tumours and normal urothelium revealed the presence of SOX9 methylation in at least 70% of the invasive cases analysed." (PMID 18087279, 2008). "Inactivation by hypermethylation of SOX9, a gene reported to be a potential tumour suppressor, would be justified to be a poor outcome prognosticator." (PMID 18087279, 2008).
tumor (continued). "The developing tumour was analysed by light and electron microscopy and by immunocytochemical localization of transcription factors SOX9 and c-kit, glial fibrillary acidic protein (GFAP) and type IV collagen." (PMID 10389991, 1999). "To dissect the heterogeneity and cell-cell interactions underlying SOX9 mutation-driven CRC progression, we integrated single-cell RNA sequencing (scRNA-seq) data of 23 CRC tumor samples with bulk sequencing and mutation data from The Cancer Genome Atlas (TCGA) using the Scissor algorithm." (PMID 42218401, 2026). "Thus, SOX9 suppression in the case of these three oncogenes has a contradictory effect, enhancing some drivers of tumor growth and suppressing others." (PMID 40141294, 2025). "Furthermore, immunohistochemical analysis of normal, adjacent, and tumor tissues collected from patients with cancer confirmed elevated SOX9 expression in tumor tissues." (PMID 39523731, 2025). "The observed discrepancies between studies may stem from the multifaceted roles of SOX9 in GC, influenced by factors, such as population characteristics, tumor stage, degrees of differentiation, and potential expression-level-dependent effects." (PMID 39907598, 2025). "Sox9 was identified as a marker of this transition and key player in tumor growth." (PMID 41223283, 2025). "Finally, a proof-of-concept drug screen aimed at reducing Sox9 expression in tumor cells identified 12 FDA-approved drugs." (PMID 41223283, 2025). "Notably, it is uncovered that amphiregulin (AREG) derived from iCAFs promotes tumor stemness by upregulating the expression of SOX9 in tumor cells, and contributes to drug resistance via the AREG‐ERBB2 axis." (PMID 39950944, 2025). "Additionally, immunohistochemical analysis of subcutaneous tumor tissues revealed that THZ2 treatment decreased SOX9 expression, whereas TMZ treatment increased it." (PMID 40843352, 2025). "Finally, our study provides support for the view that EMT and stemness phenotypes contribute to tumor progression and metastasis in vivo in CRCs that have lost SOX9 expression, but the phenotypes observed likely reflect a continuum and not a binary switch." (PMID 40179020, 2025). "We demonstrate that SOX9 may influence critical factors, such as tumor size, differentiation, vascular and perineural invasion, TNM staging, and lymph node or distant metastases in GC." (PMID 39907598, 2025). "In contrast to the lack of binding around GE and interneuron genes, we observed strong signal for Foxr2 binding on promoters and regulatory elements of Sox9 and Sox10 in regions of open chromatin specific to glial-like tumor cells, correlating with expression of those genes in the RNA-seq data." (PMID 39495206, 2025). "Both tumor suppressor and oncogenic functions of SOX9 have been suggested, including in CRC." (PMID 40179020, 2025). "As Sox9 inhibition in mouse MPNST cells reduced tumor growth after transplantation in nude mice, we hypothesized that compounds inhibiting Sox9 expression would impede MPNST development." (PMID 41223283, 2025). "It turned out that both in the group of genes with increased expression in PAAD relative to the normal pancreas and in the group of genes with decreased expression in the tumor, the expression of part of genes is up-regulated and the other part of genes is down-regulated during SOX9 knockdown." (PMID 40141294, 2025). "Given its critical role in tumor dormancy and NK cell evasion, SOX9 is a key strategic target." (PMID 41293317, 2025). "For example, both superficial and deep MRs from MEL18 and MEL25 contained neighboring tumor cells expressing SOX9, SOX10 and MART1 in different combinations and intensities, consistent with frequent changes in molecular programs associated with these melanocyte markers." (PMID 40667360, 2025).
tumor (continued). "In addition, studies on disseminated tumor cells (DTCs) have shown that retinoic acid (RA) signaling can induce tumor dormancy by modulating SOX9 expression, and NK cell receptors (such as NKG2D ligands and HLA class I genes) also significantly decreased." (PMID 41293317, 2025). "Notably, SOX9’s role in inflammatory and degenerative diseases contrasts with its pro-tumor function in cancers." (PMID 41293317, 2025). "Research indicated that SOX9 can inhibit dendritic cells from infiltrating tumor tissue." (PMID 40342816, 2025). "SOX9 is increasingly recognized to be a potent mediator of tumor cell invasiveness, so it is possible this could explain the somewhat more mesenchymal/invasive appearance of these tumors." (PMID 40879132, 2025). "ALDH1 and ALDH1/SOX9 expressing cells were significantly more prevalent in grade 3 tumor biopsies." (PMID 39888143, 2025). "At the same time, long-term androgen deprivation therapy (ADT) may indirectly weaken the anti-tumor immune response by enriching a subpopulation of club cells characterized by high SOX9 and low AR (SOX9high ARlow)." (PMID 41293317, 2025). "Furthermore, we have identified the upregulation of SOX2 as a potentially critical mechanism downstream of SOX9 loss, likely contributing to the observed EMT changes, CSC phenotypes, and tumor progression." (PMID 40179020, 2025). "We next studied whether the chemotherapy-induced SOX9 upregulation is recapitulated in primary tumor samples." (PMID 41031891, 2025). "One strategy is to knock out SOX9, which disrupts tumor immunity and dormancy." (PMID 41293317, 2025). "However, SOX9 status is typically assessed through immunohistochemistry, which requires invasive tumor samples to be obtained via surgery or biopsy." (PMID 40428248, 2025). "SOX9 was highly expressed in a range of malignant tumor tissues, including GBM." (PMID 40692865, 2025). "Importantly, we found that inflammatory CAFs (iCAFs) enhance tumor stemness by upregulating SOX9 and OLFM4, contributing to drug resistance and cell proliferation through the AREG‐ERBB2 signaling pathway." (PMID 39950944, 2025). "Furthermore, SOX9 influences macrophage polarization towards a pro-tumor M2 phenotype, fostering an immunosuppressive microenvironment." (PMID 41293317, 2025). "Furthermore, diminished Wnt/β-catenin correlates with reduced levels of its effector SOX9 and impaired tumor cell proliferation in metastatic SCCs." (PMID 40399946, 2025). "A 60% reduction in Sox9 mRNA levels before grafting was shown to significantly impede tumor growth." (PMID 41223283, 2025). "Thus, SOX9 modulates macrophage polarization, pyroptosis, and activity, playing significant roles in tumor immune evasion." (PMID 41293317, 2025). "Notably, we also found that IL11+CD10+ iCAFs were a key component of CSC niche that drive tumor stemness in CSCs by upregulating the expression of SOX9 and OLFM4, leading to drug resistance via the AREG‐ERBB2 signaling pathway." (PMID 39950944, 2025). "Despite the human CRC tumor data indicating SOX9 could function as a tumor suppressor gene, most functional studies and data reflect work with SOX9 ectopic overexpression approaches in tissue culture settings." (PMID 40179020, 2025). "Notably, we observed CD44v6 expression in the same cells that express the progenitor/stem cell marker SOX9 in both human and murine tumours, supporting the idea that CD44v6+ cells represent a progenitor-like subpopulation in liver tumorigenesis." (PMID 41168417, 2025). "To assess whether this increase in SOX9 expression is found in every cell and patient tumor, we plotted it at a single-cell and patient-specific pseudo-bulk RNA level." (PMID 41031891, 2025). "Two-dimensional VisiumTM maps show concentric aggregates of M2‐TAMs and osteoclast-like mononucleated giant cells girdling necrotic bone trabeculae, while MARCOhigh macrophages preferentially align along peri-vascular tracks, often in direct apposition to SOX9+ stem-like tumour cells." (PMID 40740859, 2025).